ITGA4 (integrin subunit alpha 4)
Diseases named in the same sentence as ITGA4 in open-access papers (continued):
Sharing a sentence is not in itself a finding about the gene and the disease.
tumor (111 papers, 2007 to 2026). "We evaluated the diagnostic value of ITGA4 in distinguishing tumor from normal tissues using ROC curves." (PMID 40012546, 2025). "CD49D/Itga4 has been identified as a reliable marker for distinguishing bone marrow-derived macrophages from tumor-associated microglia." (PMID 40076738, 2025). "All five algorithms consistently showed that ITGA4 was markedly associated with immune cell infiltration across various tumors, particularly with tumor-associated macrophages (TAMs), M1 and M2 macrophages, and CD4+ and CD8+ T cells." (PMID 40012546, 2025). "Tumor-associated CD163+ macrophages expressing VCAM1 interacted with tumor-associated erythroid cells expressing ITGA4." (PMID 37894821, 2023). "ITGA4 was significantly associated with N classification (P = 0.031), tumor location (P = 0.033), WHO classification (P = 0.007), and poor prognosis in mRNA level." (PMID 36254221, 2022). "Tumour ITGA4 expression was also associated with the high‐risk category of the NIH classification and with poor GIST‐specific and overall survival." (PMID 29377440, 2018). "Besides, higher ITGA4 expression was linked to advanced tumor grades and stages, indicating its role in malignant progression." (PMID 40012546, 2025). "We found further that high GIST ITGA4 expression in the tumour cells is associated with unfavourable prognosis of patients and undertook functional studies to investigate whether inhibition of ITGA4 with siRNA or two VLA‐4‐specific inhibitors prevents invasion of GIST cells." (PMID 29377440, 2018). "In the majority of tumor types, a significant positive correlation is observed between ITGA4 and immune-related scores." (PMID 41602372, 2026). "Tregs, CAFs, and endothelial cells, which support tumor growth, metastasis, and immunosuppression, were also significantly positively correlated with ITGA4." (PMID 40012546, 2025). "ITGA4 is predominantly identified in tissue samples, showing high specificity and establishing it as a trusted marker for direct access to tumor DNA, guaranteeing accurate detection." (PMID 41311876, 2025). "Itga4, integrin subunit alpha 4, was reported to upregulate in three T cell subsets such as Tregs in age-related tumor growth." (PMID 40282557, 2025). "The recruitment of CD4+ and CD8+ T cells to tumor sites is likely influenced by this inflammatory milieu and regulated by ITGA4." (PMID 40012546, 2025). "Given the significant impact of tumor cell heterogeneity and stemness on malignancy and immunotherapy sensitivity, we explored the relationship between ITGA4 and related indices across multiple cancers." (PMID 40012546, 2025). "As the role of integrins in the TME is complex and varies according to tumor heterogeneity, further research is needed to elucidate the signaling mechanisms related to ITGA4." (PMID 40012546, 2025). "In GC, high ITGA4 expression was related to poor prognosis, promoted tumor proliferation and migration, and enhanced immune cell infiltration." (PMID 40012546, 2025). "These analyses deepen our understanding of ITGA4’s role in tumor biology and microenvironments, offering crucial insights for developing targeted therapies and predicting tumor behaviors." (PMID 40012546, 2025). "These tumor subtypes cooperatively drive CD8+ T cell exhaustion through the MDK–(ITGA4+ITGB1), MIF–(CD74+CXCR4), and TGF-β signaling pathways." (PMID 40948762, 2025). "These efforts demonstrate ITGA4’s potential as a significant biomarker in oncology, highlighting its potential role in tumor immunotherapy." (PMID 40012546, 2025). "Significant correlations were also noted between ITGA4 and other tumor heterogeneity markers such as HRD, LOH, MATH, NEO, ploidy, and tumor purity across multiple cancer types." (PMID 40012546, 2025). "Given the TME’s complex role in tumor malignancy and treatment response, targeting ITGA4 to mitigate TME-induced immunosuppression holds promise for improving anti-cancer efficacy." (PMID 40012546, 2025).
tumor (continued). "As TME has an important impact on tumor activity and response to treatment, we analyzed the correlation between ITGA4 expression and TME scores, revealing significant positive correlations with StromalScore, ImmuneScore, and ESTIMATEScore." (PMID 40012546, 2025). "ITGA4 expression was generally low in normal tissues but varied significantly across tumor types, with higher levels in advanced stages and grades." (PMID 40012546, 2025). "We analyzed the correlation of FN1, ITGA4, ITGA5, ITGAV, ITGB1, ITGB3 and ITGB6 with disease status, risk of tumor recurrence according to the 2015 American Thyroid Association guidelines, and patient outcome." (PMID 40423510, 2025). "Predictive nomogram model further validated the clinical decision-making value of ITGA4, showcasing its excellent potential as a tumor biomarker and therapeutic target." (PMID 40012546, 2025). "Among these genes, several immune system genes, such as COL18A1, S100A2, ITGA4, HLA‐C, and ADCYAP1, have previously been linked to tumor progression in PCa." (PMID 39162297, 2024). "Of note, the CD28+ cluster was detected also in the tumor, and accordingly it was enriched by ITGA4 (CD49), CCR5 and CD44, all contributing to CD8+ T-cell infiltrative capacity." (PMID 37898752, 2023). "IGF2-expressing tumor cells interact with IGF1R-expressing tumor-associated erythroid cells in the patient, and tumor cells expressing SPP1 interact with tumor erythroid cells expressing ITGA4." (PMID 37894821, 2023). "Univariate Cox regression analysis showed that ITGA4 (P = 0.011), lymph node metastasis rate (P < 0.001), and tumor location (P = 0.003) were correlated with prognosis." (PMID 36254221, 2022). "While the WT 5TGM1-GFP tumor bearing mice were euthanized at week three when there was terminal disease burden, the Itga4 (α4) KO 5TGM1-GFP mice were euthanized at week three and week six respectively for ex vivo tissue bio distribution." (PMID 34996933, 2022). "ITGA4 has been proved to be involved in cell proliferation, apoptosis, adhesion, and migration, which promoting tumor progression." (PMID 36254221, 2022). "We evaluated the expression of ITGA4 through immunohistochemistry, which is mainly expressed in the cytoplasm of tumor cells." (PMID 36254221, 2022). "Other markers have also demonstrated the capacity to differentiate between microglia and BMDMs such as CD49D/integrin subunit alpha 4, a marker exclusive to tumor-infiltrating BMDMs." (PMID 36761422, 2022). "Biologically, mice bearing Itga4 (VLA4) KO tumors demonstrated an enhancement in survival likely due to differential tumor cell distribution in vivo." (PMID 34996933, 2022). "In the subgroup analysis of patients with early tumor diagnosis (26 patients with T1-2N0), we found that ITGA4 had a strong prognostic power for future disease recurrence." (PMID 32937734, 2020). "Noteworthy, ITGA4 showed a strong prognostic power for future disease recurrence in the subgroup analysis of patients with early stage tumor diagnosis." (PMID 32937734, 2020). "The migration of immune cells to tumor environment is the first step to exert their effects, therefore we selected the genes related to leukocyte migration, including IL-1β, ITGA4, ITGB2, ITGB7, CAV1, and MAG." (PMID 32358484, 2020). "In LADC, a hypoxic tumor microenvironment can potentially cause the dysregulation of NOTCH1 and ITGA4 signaling pathways." (PMID 31217907, 2019). "In summary, ITGA4 is highly expressed in GISTs as compared with most other human tumour types and most normal tissues." (PMID 29377440, 2018). "However, ITGA4’s specific functions in cancer progression and the tumor microenvironment (TME) remain elusive." (PMID 40012546, 2025). "Besides, in GC cases, ITGA4 promotes tumor cell proliferation, invasion and metastasis, while also contributing to inflammatory responses and leading to adverse outcomes." (PMID 40012546, 2025).
tumor (continued). "Subsequently, we determine whether the tumor cells-secreted SPP1 could influence CD8+T cells function by regulating ITGA4/ITGB1 expression." (PMID 40665335, 2025). "ITGA4 positively correlated with immune cell infiltration, immune regulatory genes, chemokines, and might reduce microsatellite instability (MSI) and tumor mutation burden (TMB) by promoting MMR gene expression." (PMID 40012546, 2025). "Additionally, analysis from the CPTAC database revealed that ITGA4 protein expression was higher in tumor tissues compared to normal tissues in COAD, OV, KIRC, PAAD, HNSC, and GBM, while it was lower in LIHC, LUAD, and BRCA." (PMID 40012546, 2025). "ITGB1 and ITGA4 are drivers of heterotypic T cell clustering with tumor cells." (PMID 40955669, 2025). "Aberrant ITGA4 expression possibly creates an inflammatory environment that polarizes M1 macrophages to M2 macrophages, promoting immunosuppression and recruiting other immune cells to the tumor site." (PMID 40012546, 2025). "Additionally, we investigated ITGA4’s influence on tumor immunity, heterogeneity, stemness, drug sensitivity." (PMID 40012546, 2025). "In addition, ITGA4 was highly correlated with poor pathological features such as N classification (P = 0.031), tumor location (P = 0.033), and WHO classification (P = 0.007)." (PMID 36254221, 2022). "The delineation of ITGA4 as a poor prognostic factor was not surprising since increased expression of integrin α4β1 is associated with tumor progression and ECM components secreted by CAFs bind integrins to activate pro-tumorigenic pathways." (PMID 35739492, 2022). "In terms of tumor evolution, this finding might reflect advantage for the cells in which elevation of ITGA4 expression was occasionally “preventively prohibited” by its promoter methylation." (PMID 33500458, 2021). "Recently, using multiple genetic lineage tracing in transgenic (GEMM-shP53) and syngeneic GL261 mouse models, Bowman and collaborators have demonstrated that microglia specifically repress Itga4 (CD49D), enabling the distinction between microglia and monocyte-derived macrophages in murine tumours." (PMID 31973030, 2020). "Notably, our study identified ITGA4 as a potential prognostic and immunotherapeutic biomarker, which holds bidirectional implications, highlighting the importance to consider its diverse expression and functions across tumor types." (PMID 40012546, 2025). "We hypothesize that abnormal ITGA4 expression may foster an adverse inflammatory environment in tumors, leading to decreased M1 macrophage activation while facilitating their polarization towards the tumor-promoting M2 phenotype." (PMID 40012546, 2025). "Indeed, the question to discuss in the context of ITGA4 abnormal hypermethylation in BC, is what the reason may be for the gene negligibly expressed in the normal tissue to become hypermethylated in the tumor of the same organ." (PMID 33500458, 2021). "On the one hand, tumor cell C1_EGFR+ and C2_STAT1+ directly act on CD8T_GNLY+ through the MDK–(ITGA4+ITGB1) axis and the MIF–(CD74+CXCR4) axis to promote tumor proliferation." (PMID 40948762, 2025). "Aligning with functional enrichment analysis results, we found that ITGA4 was significantly positively correlated with three TME indicators, suggesting its crucial impact on tumor cells, stromal components, and immune cells." (PMID 40012546, 2025). "This indicates a potential pivotal role of ITGA4 in modulating the TME, particularly in the interactions between tumor cells and the surrounding stroma and immune cells." (PMID 40012546, 2025). "Ligand-receptor analysis between macrophages and tumor cells identify C5/C5AR1,SPP1/ITGA4, and TF/TFRC as the ligand-receptor signaling mechanism driving these niche-DE genes." (PMID 38217002, 2024).
tumor (continued). "In particular, the interaction between Midkine (MDK, secreted by tumor cells) and a number of MDK-receptors (ITGA4, ITGA6, ITGB1, NCL, LRP1) on CD8+ T cells appears to be a recurrent immunosuppressive pathway seen across all three patients." (PMID 36973261, 2023). "Remarkably, analyses of MDK receptor-expressing CD8 cells (ITGA4, ITGB1, NCL) showed the opposite trend, with an increase in dysfunctional and reduction in the proliferative (tumor-targeting) populations." (PMID 36973261, 2023). "Less number of Itga4 (α4) 5TGM1-GFP KO2 cells were detected in the BM than 5TGM1-GFP WT cells after 15 and 30 min of i.v. tumor injection (p = 0.016 and p = 0.043, respectively)." (PMID 34996933, 2022). "The SPP1 receptor ITGB1 was upregulated in tumor-derived NK cells, while another SPP1 receptor ITGA4 was upregulated in tumor-derived CTL-1 cells." (PMID 36180422, 2022). "The expression of ITGA4, ITGA8, ITGB2, ITGB7 and ITGB8 was correlated with the infiltration of all types immune cell and tumor purity in the SKCM TIME." (PMID 34660316, 2021). "Regarding tumor location, we observed that FIT showed a higher sensitivity for distal CRC, while ITGA4, Fn, and Pa performed better in discriminating proximal CRC from healthy subjects." (PMID 34689777, 2021). "Results illustrated that ITGA2, ITGA3, ITGA4, ITGA6, ITGA11, and ITGAV transcripts were increased in ESCC tumour tissues (n = 95) compared with normal tissues (n = 11)." (PMID 34709754, 2021). "Differential methylation of the ITGA4, SFN, ITGA2, and PIK3R1 genes allowed the discrimination between normal and tumour tissue and correlated with patient survival." (PMID 34944974, 2021). "We next verified the protein levels of the integrin α‐subunits suggested to be differentially represented between samples at the mRNA level, including ITGA2, ITGA3, ITGA4, ITGA6, ITGA11, and ITGAV using 10 paired (tumour and adjacent) ESCC patient tissues." (PMID 34709754, 2021). "Results showed that ITGAV (10/10), ITGA2 (7/10), ITGA3 (8/9), ITGA4 (7/10), ITGA6 (7/8), and ITGA11 (7/9) protein levels were increased in tumour tissues compared with adjacent tissues." (PMID 34709754, 2021). "The sensitivity of detecting Ta tumor was also superior to the reported methylation assays by DLX1 and ITGA4 (50.0–84.6%) and BCL2, CDKN2A and NID2 (61.1%)." (PMID 33902700, 2021). "As expected, integrins interacting with ECM components are expressed in a cell‐type‐selective fashion, such as ITGA4, ITGAL and ITGB7 by immune cells, while tumour and stromal cells strongly expressed ITGA3, ITGAV and ITGB1/4/5/6/8." (PMID 34841720, 2021). "The median ITGA4 gene to control G6PD gene mRNA expression ratio in GIST was 6.7 (range = 0.18–15.94, P = 0.002) and in other tumours 2.1 (range = 0.10–6.23)." (PMID 29377440, 2018). "Under normoxia, MMP1 and integrin (ITGA4) were elevated in TNF-α and TNFα/IL-1β clones; these can degrade the ECM component and play a role in the development of tumour metastasis." (PMID 26759080, 2016). "This included EC-specific proteins (e.g. COL1A1, FBN1), tumour-specific proteins (e.g. ITGB1) and proteins up-regulated in both cell types (FN1, THSB1, CD44, ITGA4, CTGF)." (PMID 27049916, 2016). "This suggests that elevated ITGA4 expression could decrease MSI and TMB mediated by MMR, potentially complicating tumor responsiveness to immunotherapy." (PMID 40012546, 2025). "Meanwhile, targeting ITGA4 in combination with ICIs may modulate the TME, reduce inflammation and immune evasion, and enhance anti-tumor immune cell infiltration and response." (PMID 40012546, 2025). "Across both tumor clusters, MDK–(ITGA4+ITGB1) and MIF–(CD74+CXCR4) emerged as prominent axes." (PMID 40948762, 2025). "Additionally, MDK-SDC2 and MDK-(ITGA4+ITGB1) signals from fibroblasts and tumor cells were only received by CPVLhi TAMs." (PMID 39776914, 2024). "Additionally, Midkine (MDK) released from tumour cells interacted with SDC4, SDC1, NCL, ITGA4, ITGA6 and ITGB1 on immune cluster." (PMID 39187937, 2024).
tumor (continued). "The in vivo phenotypic studies of Itga4 (α4) KO 5TGM1-GFP and WT 5TGM1-GFP, indicates that VLA4 on MM cells participates in BM homing, extramedullary manifestation, BM tumor burden, and survival, emphasizing the importance of MM-BM microenvironment interaction contributed by VLA4." (PMID 34996933, 2022). "We found that differential methylation of the ITGA4, SFN, ITGA2, PIK3CD, and PIK3R1 genes allowed the discrimination between normal and tumour tissue evidencing that all 12 CpGs identified were good to excellent diagnostic biomarkers with AUC > 0.8 in two independent cohorts." (PMID 34944974, 2021). "Therefore, the effects of ITGA4 knock‐down and selective integrin alpha 4 beta 1 (VLA‐4) inhibitors on tumour cell proliferation and invasion were investigated in three GIST cell lines." (PMID 29377440, 2018). "We found a positive association between GIST ITGA4 expression and a high tumour mitotic count in a large GIST patient series, but knock‐down of ITGA4 expression did not influence cell proliferation in GIST cell lines." (PMID 29377440, 2018). "High expression was present in 14 (9.5%) GISTs, low expression in 48 (32.7%), and 85 (57.8%) tumours were negative in immunostaining for ITGA4." (PMID 29377440, 2018). "The decreased expression of the adhesion molecules Itga4 and Vtn in the SCC lesions from the CCL3-/- mice may be indicative of the fact that CCL3 activate neoplastic cell adhesion and motility within the tumour microenvironment as described for other tumours." (PMID 28881626, 2017). "Of note, while TGFB1, a master regulator of the malignant phenotype, appeared to be mostly up-regulated in the tumour, its activators THBS1, FN1 and ITGA4 were strongly induced in tumor cells and ECs, highlighting a concerted molecular interaction to regulate cellular activity." (PMID 27049916, 2016). "Tumor stromal pathways are also in evidence with the common genes including; TLR4, TLR7, HLA-DRA, HLA-DQA1, CXCR4, FOS and TGFB2 (immune surveillance and chemokine pathways) and NF2, ITGA7, PGF, ITGA4, PDGFD and PARVA (focal adhesion)." (PMID 23226201, 2012). "Not only have known tumor suppressor genes like Cdkn2a (p16), Itga4 (α 4-integrin), and Igfbp7 been identified as targets of aberrant methylation in cancer by RLGS, but also novel tumor suppressor genes such as TCF21, SLC5A8, ID4, BMP3B, and SOCS1 have been identified by RLGS." (PMID 18053125, 2007). "GO and KEGG enrichment analyses showed that ITGA4 was enriched in cell adhesion, leukocyte migration and hematopoietic processes and participated in the PI3K-Akt signaling pathway, which is related to tumor cell migration, adhesion, tumor angiogenesis and extracellular matrix degradation." (PMID 36879313, 2023). "Strong association of abnormal ITGA4 hypermethylation with the HER2 positive tumors (p = 0.0025) suggests that simultaneous presence of both HER2 and integrin α4 receptors is not beneficial for tumor cells." (PMID 33500458, 2021). "For the ITGA4, ITGA9, NID1 and NID2 genes for which XmaI-RRBS data are available, we have calculated the relative fractions of methylated and nonmethylated alleles in tumor samples, in respect to HER2 expression in tumors." (PMID 33500458, 2021). "Besides, ITGA4/AL/AM/AX and ITGB2/B7 obviously correlate with TILs, particularly strongly correlate with monocyte, M2 macrophage and exhaustion T cells, which usually play pro-tumor and immunosuppressive role in cancer." (PMID 32765584, 2020). "However, they may also promote tumor progression through GAS6-AXL and ANXA1-FPR1 signaling, interacting with fibroblasts, endothelial cells, and monocytes, while the role of MDK-SDC2 and MDK-(ITGA4+ITGB1) signals remains to be elucidated." (PMID 39776914, 2024).